PAPSS1 (3'-phosphoadenosine 5'-phosphosulfate synthase 1)
Description:
Bifunctional enzyme with both ATP sulfurylase and APS kinase activity, which mediates two steps in the sulfate activation pathway. The first step is the transfer of a sulfate group to ATP to yield adenosine 5'-phosphosulfate (APS), and the second step is the transfer of a phosphate group from ATP to APS yielding 3'-phosphoadenylylsulfate (PAPS: activated sulfate donor used by sulfotransferase). In mammals, PAPS is the sole source of sulfate; APS appears to be only an intermediate in the sulfate-activation pathway. Required for normal biosynthesis of sulfated L-selectin ligands in endothelial cells.
Synonyms: SK1; ATPSK1; PAPSS
Tractability: Small molecule: a structure with a bound ligand is known; it has a high-quality binding pocket. PROTAC: ubiquitination databases record sites on it; its protein half-life has been measured.
Target class: Enzyme; Transferase
Gene: Protein-coding gene on chromosome 4 (107,590,276 to 107,720,395, reverse strand). Ensembl gene ENSG00000138801.
Subcellular location (Human Protein Atlas): Mitotic chromosome; Nucleoli rim; Nucleoplasm
Pathways (Reactome):
Metabolism: Metabolism of ingested H2SeO4 and H2SeO3 into H2Se; Transport and metabolism of PAPS
Disease: Signaling by BRAF and RAF1 fusions
Gene Ontology:
Molecular function: adenylylsulfate kinase activity; protein binding; protein homodimerization activity; sulfate adenylyltransferase (ATP) activity; nucleotidyltransferase activity; ATP binding
Biological process: 3'-phosphoadenosine 5'-phosphosulfate biosynthetic process; sulfate assimilation; skeletal system development
Cellular component: cytosol; nucleus; cytoplasm
Genetic constraint (gnomAD): Loss-of-function variants: 37 observed, 49.49 expected, observed/expected ratio (o/e) 0.75, 90% interval 0.57 to 0.98. The upper end of that interval is the gene's LOEUF score, 0.98, which puts it in group 4 of 6, group 1 being the genes least tolerant of losing a copy. Missense variants: 542 observed, 672.99 expected, observed/expected ratio (o/e) 0.81, 90% interval 0.75 to 0.87. Synonymous variants: 225 observed, 226.47 expected, observed/expected ratio (o/e) 0.99, 90% interval 0.89 to 1.11.
Homologues: Orthologues: chimpanzee PAPSS1 (100% identical), macaque PAPSS1 (99% identical), dog PAPSS1 (99% identical), mouse Papss1 (99% identical), pig PAPSS1 (99% identical), rabbit PAPSS1 (99% identical), rat Papss1 (98% identical), tropical clawed frog papss1 (91% identical), guinea pig PAPSS1 (90% identical), zebrafish papss1 (87% identical), Drosophila melanogaster Papss (62% identical), Caenorhabditis elegans pps-1 (58% identical). Paralogues in human: PAPSS2 (76% identical).
Diseases named in the same sentence as PAPSS1 in open-access papers:
PAPSS1 is named in the same sentence as 20 diseases in open-access papers, as found by Europe PMC text mining. Sharing a sentence is not in itself a finding about the gene and the disease. The quoted sentences say what the papers report.
breast carcinoma (4 papers, 2013 to 2016). "According to the cBioPortal database, only approximately 7% of breast cancers and 2% of lung adenocarcinoma harbour PAPSS1 amplifications and mutations." (PMID 27322429, 2016). "We have also searched the cBioPortal database which indicates that 6.9% of breast cancer patient xenografts have PAPSS1 amplification and about 2% of lung adenocarcinomas have PAPSS1 mutations." (PMID 26220590, 2015). "PAPSS1 might be important for growth of estrogen-sensitive breast cancer cells as a recent study revealed that overexpression of SULT1E1 and PAPSS1 resulted in growth inhibition." (PMID 23476785, 2013).
hepatocellular carcinoma (2 papers, 2016 to 2023). A malignant tumor that arises from hepatocytes. "Also, PAPSS1 has been suggested as a candidate HCC-susceptibility gene and correlated with poor survival in patients with familial or early onset hepatocellular carcinoma (HCC)." (PMID 37684671, 2023).
lung adenocarcinoma (2 papers, 2015 to 2022). A carcinoma that arises from the lung and is characterized by the presence of malignant glandular epithelial cells. "To evaluate the impact of PAPSS1-KO on HepS biosynthesis in other cell lines, we additionally obtained PAPSS1-KO clones using human gastric adenocarcinoma (AGS) cells and lung adenocarcinoma A549 cells." (PMID 35854076, 2022).
ovarian carcinoma (2 papers, 2016 to 2023). A malignant neoplasm originating from the surface ovarian epithelium. "Kaplan–Meier survival analysis revealed a longer progression-free survival (PFS) and overall survival (OS) in ovarian cancer patients with low PAPSS1 expression and high ESR1 expression than those with low ESR1 and high PAPSS1." (PMID 37684671, 2023). "An inverse correlation of the gene expression between ESR1 and PAPSS1 was revealed in ROC plotter datasets of ovarian cancer." (PMID 37684671, 2023). "The aim of this study was to determine the value of targeting PAPSS1 as a cisplatin modulator in epithelial ovarian cancer (EOC)." (PMID 37684671, 2023). "Our study showed an inverse correlation of the gene expression between ESR1 and PAPSS1 in Kaplan–Meier plotter platform of ovarian cancer and platin-based chemotherapy ovarian cancer patients." (PMID 37684671, 2023). "The increased expression of PAPSS1 in human ovarian cancer was further validated by IHC analysis of an ovarian cancer tissue array, including 131 ovarian cancer tumors." (PMID 37684671, 2023). "The results of the Spearman chi-square test indicated that the high nucleus PAPSS1 was positively associated with the FIGO stage, histological subtype, platinum resistance, metastasis and recurrence in patients with ovarian cancer." (PMID 37684671, 2023). "From a therapeutic perspective, our study first identified the potential of a combinational therapy using platinum drugs and PAPSS1 inhibitors to treat ovarian cancer patients." (PMID 37684671, 2023). "Based on the present findings, we propose that PAPSS1 is a relevant oncology target in ovarian cancers and provides a novel strategy for ovarian cancer treatment." (PMID 37684671, 2023). "In this study, we found that PAPSS1 was highly expressed in ovarian cancer compared to normal tissue and was also upregulated in ovarian cancer cisplatin-sensitivity or resistance cells (A2780 and SKOV3) than in normal ovarian cells (HOSEpic)." (PMID 37684671, 2023). "In addition, an inverse correlation of the gene expression between ESR1 and PAPSS1 was observed in ROC plotter datasets of ovarian cancer." (PMID 37684671, 2023). "Besides, low PAPSS1 and high ESR1 were associated with improved PFS and OS in platin-based chemotherapy ovarian cancer patients." (PMID 37684671, 2023). "Also, according to TCGA and GTEx mRNA data, PAPSS1 showed a higher expression in ovarian cancer tissues." (PMID 37684671, 2023). "Also, low nuclear PAPSS1 and high nuclear ERα expression in EOC were associated with longer overall survival and progression-free survival in all ovarian cancer and ovarian cancer patients who received platinum-based chemotherapy." (PMID 37684671, 2023). "Both PAPSS1 and ESR1 gene expression are relatively sensitive markers for predicting the effect of platinum treatment on patients with ovarian cancer." (PMID 37684671, 2023). "The causal relationships between PAPSS1 and HCC survival has not been elucidated and the mechanism(s) by which PAPSS1 sensitizes NSCLC and ovarian cancer cells to DNA damage are yet to be defined." (PMID 27322429, 2016).
glioma (1 paper, 2018). A benign or malignant brain and spinal cord tumor that arises from glial cells (astrocytes, oligodendrocytes, ependymal cells). "Therefore, PAPSS-1 and PAPSS-2 provided abundant PAPS substrate for sulfotransferases which leads to the increase of pAp production in gliomas." (PMID 30283018, 2018).
hepatoblastoma (1 paper, 2024). Hepatoblastoma (HB) is a malignant hepatic tumor and is the most common pediatric liver cancer. "Hepatoblastoma tumor cells exhibited upregulation of purine metabolism through enhanced expression of ENTPD1, PDE4C, PDE5A, and PAPSS1." (PMID 39684755, 2024).
liver cancer (1 paper, 2025). An epithelial or non-epithelial malignant neoplasm that arises from the liver. "Polymorphisms within the ATP sulfurylase domain of the PAPSS1 gene are also strongly correlated with both liver cancer susceptibility and the efficacy of drug therapy." (PMID 39963268, 2025).
lung carcinoma (1 paper, 2015). "At this time, there is a lack of gene expression data derived from lung cancer patients which would suggest that PAPSS1 levels are important in terms of predicting response to cisplatin-containing cocktails." (PMID 26220590, 2015).
non-small cell lung carcinoma (1 paper, 2023). A group of at least three distinct histological types of lung cancer, including non-small cell squamous cell carcinoma, adenocarcinoma, and large cell carcinoma. "Moreover, recent studies suggested that silencing of PAPSS1 can enhance cisplatin activity in non-small cell lung cancer; also, PAPSS1 expression was negatively correlated with survival rate in patients receiving platinum-based chemotherapy." (PMID 37684671, 2023).
ovarian tumor (1 paper, 2023). "Ovarian tumor xenografts with PAPSS1-targeting shRNAs was determined to be effective at slowing the rate of tumor growth in animals, and PAPSS1 suppression/cisplatin combination was superior to cisplatin in the inhibition of tumor growth." (PMID 37684671, 2023).
viral infections (1 paper, 2022). "Hence, our cumulative findings suggested that PAPSS1 influences HepS biosynthesis, contributing to viral infections by assisting the binding of virus particles." (PMID 35854076, 2022).
cancer (7 papers, 2015 to 2025). A tumor composed of atypical neoplastic, often pleomorphic cells that invade other tissues. "PAPSS1 and PAPSS2 exhibited high mutation frequencies across more than 10 cancer types, with PAPSS1 mutated in 5.8% of UCEC cases." (PMID 41441975, 2025). "The exact mechanism through which PAPSS1 enhances the activity of the other cytotoxic agents, molecularly targeted drugs, and cancer immunotherapy drugs need to be further explored." (PMID 37684671, 2023). "when attempting to understand what the role of PAPSS1 is in cancer we recognized a dearth of information." (PMID 27322429, 2016). "Given the biological role of PAPSS1, which synthesizes the biologically active form of sulfate, one can speculate on the role of sulfur metabolism and homeostasis in cancer cells when they are first exposed to cytotoxic agents." (PMID 37684671, 2023). "At the IC10 of cisplatin (i.e. the dose of cisplatin that would cause 10% cell death), PAPSS1 inhibition reduced long-term viability of some cancer cells by 99% compared to non-targeting controls." (PMID 27322429, 2016). "Given the biological role of PAPSS1, one can speculate on the role of sulfur metabolism and homeostasis in cancer cells when they are first exposed to cytotoxic agents such as cisplatin." (PMID 26220590, 2015). "This interaction between PAPSS1 silencing and enhancing the activity of several distinct classes of commonly used anticancer agents is unique and is worth pursuing therapeutically in cancers where these drugs are commonly used." (PMID 26220590, 2015). "And the PAPSS1, MAP3K11, and SPRED1 showed lower IHC scores in KIRC compared with para-cancer samples (p<0.05)." (PMID 38217548, 2024). "The following IHC indicated that the PAPSS1, MAP3K11, and SPRED1 showed lower IHC score in KIRC compared with para-cancer samples." (PMID 38217548, 2024). "The immunohistochemistry indicated that the PAPSS1, MAP3K11, and SPRED1 showed lower IHC score in KIRC compared with para-cancer samples." (PMID 38217548, 2024). "This sensitization was selective for cancer cells as strong inhibition of PAPSS1 at the protein level did not sensitize normal bronchial epithelial cells to cisplatin treatment." (PMID 27322429, 2016). "Another discovery using TCGADEPMAP was the prediction of PAPSS1 synthetic lethality with deletion of PAPSS2 and the neighboring tumor suppressor, PTEN, which were frequently co-deleted in TCGA patient tumors (43% co-incidence) yet were largely unaffected in cancer cell lines." (PMID 39009815, 2024).
tumor (5 papers, 2015 to 2024). "IHC staining showed the expression of PAPSS1 in the tumor xenografts derived from A2780 and SKOV3 cells increased after DDP administration compared with the PBS and shSCR + PBS groups." (PMID 37684671, 2023). "Furthermore, we demonstrated that suppression of PAPSS1 expression inhibits tumor progression by enhancing the in vivo sensitivity of A2780 and SKOV3 cells to cisplatin." (PMID 37684671, 2023). "Finally, PAPSS1 showed increased PAPSS1 expression in tumor and metastatic tissues of the ovary compared to normal tissues." (PMID 37684671, 2023). "Finally, PAPSS1/PAPSS2 synthetic lethality was confirmed in vivo, as demonstrated by a significant tumor growth reduction of UMUC3 tumors without PAPSS1 and PAPSS2 compared to control tumors lacking only PAPSS2." (PMID 39009815, 2024). "After controlling for tumor lineage, PAPSS1 dependency in TCGADEPMAP was correlated with significantly worse OS (hazard ratio (HR) = 0.61, P = 0.0004) in patients with PAPSS2 deletion, demonstrating that PAPSS1 is a synthetic lethality target with potentially high translational impact." (PMID 39009815, 2024).
metabolic disease (1 paper, 2018). A congenital disorder (due to inherited enzyme abnormality) or acquired (due to failure of a metabolically important organ) disorder resulting from an abnormal metabolic process. "Human PAPSS2 mutations manifest with undetectable DHEA sulfate, androgen excess, and metabolic disease, suggesting that ubiquitous PAPSS1 cannot compensate for deficient PAPSS2 in supporting DHEA sulfation." (PMID 29743239, 2018).
PAPSS1 also shares sentences with these, for which no sentence is quoted: COVID-19 (2 papers); bovine tuberculosis (1); endometrial cancer (1); gastric adenocarcinoma (1); melanoma (1); small cell lung carcinoma (1).